PGR (progesterone receptor)
Diseases named in the same sentence as PGR in open-access papers (continued):
Sharing a sentence is not in itself a finding about the gene and the disease.
breast cancer (continued). "The tumor was consistent with liver metastasis (7 × 9 mm) from breast cancer and showed the same pathological characteristics: ER- and PgR-negative, HER2 3+." (PMID 28220470, 2017). "Clinically, based on the expression levels of estrogen receptor (ER), progesterone receptor (PR), and human epidermal growth factor receptor 2 (HER2), breast cancer is classified into subgroups of hormone receptor-positive, HER2-positive, and triple-negative breast cancer." (PMID 28515445, 2017). "Pre-operative progesterone treatment of breast cancer has been shown to confer survival benefits to patients independent of their progesterone receptor (PR) status." (PMID 28653288, 2017). "Triple-negative breast cancer (TNBC) accounts for 15-20% of all breast cancers and lacks oestrogen receptor (ER), progesterone receptor (PR) expression, and human epidermal growth factor receptor 2 (HER2) amplification." (PMID 28052035, 2017). "Recently, a phase II trial of bicalutamide, an androgen antagonist, has shown a clinical benefit rate of 19% in a select group of patients with ER/PgR-negative, AR-positive breast cancer." (PMID 28915596, 2017). "Among 4115 patients with ER or PgR positive and not HER2 overexpressed breast cancers, reduced cancer-free intervals were noted in patients whose tumors had lower PgR expression and higher Ki-67 value." (PMID 28356061, 2017). "It was reported that rare negative ER/PgR positive breast cancers are biologically different from ER positive/PgR positive tumors and have a poor clinical outcome." (PMID 28356061, 2017). "Although about 10-20% of breast cancers are triple negative, it would be of interest to study CD74 and CD44 in a cohort of breast cancer cells tested negative for estrogen receptors, progesterone receptor, and HER2." (PMID 29190904, 2017). "Triple-negative breast cancer (TNBC), which accounts for 10-20% of breast cancer patients, is negative for estrogen receptor (ER), progesterone receptor (PR), and human epidermal growth factor receptor 2 (HER2)." (PMID 29312562, 2017). "On the other hand, estrogen receptor (ER), progesterone receptor (PR), and C-erbB-2 (i.e. human epidermal growth factor receptor 2 [HER 2]) expression are the most important prognostic factors for management of breast cancer, particularly in metastatic disease settings and adjuvant treatment." (PMID 28596561, 2017). "Basal‐like breast cancers are characterized by high expression of basal cytokeratins, low or absent expression of estrogen receptor, progesterone receptor, and HER2." (PMID 28028927, 2017). "According to the evaluation of estrogen receptor (ER), progesterone receptor (PR) and human epidermal growth factor receptor 2 (HER-2/ERBB2/Neu), breast cancers are routinely divided into hormone receptor positive, HER-2/Neu amplified, and triple-negative breast cancer (TNBC) subtypes." (PMID 28423538, 2017). "Triple-negative breast cancer (TNBC) is a subtype of breast cancer defined by lack of expression of estrogen receptor alpha progesterone receptor and considered as the worst among all types of breast cancer." (PMID 28239299, 2017). "Breast cancer can be classified according to immunohistochemical phenotypes [i.e., presence or absence of estrogen receptor (ER), progesterone receptor (PgR), and epidermal growth factor receptor 2 (HER2)] into five subtypes." (PMID 28377926, 2017). "Among breast cancers that are both ER and PgR negative, two separate types are recognized, the triple-negative and pure HER2 tumors." (PMID 28356061, 2017). "Classifying breast cancer by only three markers (ER, PgR, HER2) is rough, and the definition of TNBC did not seem to be rigorous." (PMID 28423538, 2017).
breast cancer (continued). "Accurate determination of the predictive markers human epidermal growth factor receptor 2 (HER2/ERBB2), estrogen receptor (ER/ESR1), progesterone receptor (PgR/PGR), and marker of proliferation Ki67 (MKI67) is indispensable for therapeutic decision making in early breast cancer." (PMID 28490348, 2017). "About 15-20% of all breast cancers do not express estrogen receptor, progesterone receptor or HER2 receptor and hence are collectively classified as triple negative breast cancer (TNBC)." (PMID 27902967, 2017). "Triple-negative breast cancer (TNBC) cells, the most aggressive breast cancer subtype, lack ER and progesterone receptor (PR) expression, and do not show expression or amplification of the Her2/neu receptor." (PMID 28143606, 2017). "Results suggest that distributions of breast cancers in three clusters of mitotic activity depend on different mechanisms for ER + PgR+ and ER negative tumors." (PMID 28356061, 2017). "Triple-negative breast cancer is a specific subtype of breast cancer and it is defined clinically as lacking ER, PgR and HER2/neu." (PMID 29029467, 2017). "The MCF-7 cell line representing the luminal A breast cancer is positive for ER and PgR but negative for HER2 while BT-474 cell line is a luminal B tumor and positive for all the three receptors." (PMID 28377926, 2017). "This combination tool using PgR and Ki67 LI may be valuable for selecting patients with a good prognosis in intermediate type ER-positive/HER2-negative breast cancer." (PMID 28532429, 2017). "TNBC is a special subgroup of breast cancer characterized by lack of estrogen receptor alpha (ERα), progesterone receptor (PR) and human epidermal growth factor receptor 2 (HER2), and it accounts for approximately 15 to 20% of breast cancer patients." (PMID 28583190, 2017). "Furthermore, in breast cancer, high expression of AGR2 trends to correlate with ER positivity, PgR positivity and low histological grade." (PMID 29138453, 2017). "According to the expression status of progesterone receptor (PR), estrogen receptor (ER) and human epidermal growth factor receptor 2 (HER2), breast cancer can be divided into four major subtypes: hormone receptor (HR)+/HER2−, HR+/HER2+, HR−/HER2+ and HR−/HER2−, as previous studies have reported." (PMID 28038448, 2017). "Most patients had oestrogen receptor- and progesterone receptor-positive breast cancers; therefore, our evaluation was not representative of all immunohistochemical subtypes." (PMID 29708200, 2017). "Favorable early breast cancer was specified as tumor size <3 cm, Grading 1 or 2, negative lymph nodes, positive estrogen and/or progesterone receptor status, and manageable by BCS." (PMID 28335784, 2017). "Ten international pathology institutions participated in this study and determined messenger RNA expression levels of ERBB2, ESR1, PGR, and MKI67 in both centrally and locally extracted RNA from formalin-fixed, paraffin-embedded breast cancer specimens with the MammaTyper® test." (PMID 28490348, 2017). "Furthermore, PgR expression and Ki67 LI represent a powerful method for selecting patients with a poor prognosis among those with ER-positive/HER2-negative breast cancer." (PMID 28532429, 2017). "TNBC is a breast cancer (BC) subtype characterized by lack of progesterone receptor (PgR), estrogen receptor (ER), and human epidermal growth factor receptor 2 (HER-2) expression." (PMID 29069757, 2017). "Accounting for 15-20% of all breast carcinomas, it is characterized by the lack of the three most commonly targeted receptors in human breast cancer: the estrogen receptor, progesterone receptor, and human epidermal growth factor receptor 2 (HER2)." (PMID 29088795, 2017).
breast cancer (continued). "Histological examination confirmed breast cancer metastases, immunohistochemistry showed positive staining for estrogen receptor, negative for progesterone receptor and human epithelial growth factor receptor 2, proliferative index was 21%." (PMID 27894335, 2016). "TNBCs refer to certain breast cancers negative of estrogen receptor (EsR) and progesterone receptor (PgR) expression, as well as Her-2/Neu receptor overexpression." (PMID 27690302, 2016). "BRCA-positive breast cancers were more likely to be ER-negative and/or PgR-negative and less likely to display c-erbB2 overexpression than either BRCA-wild type or sporadic tumors." (PMID 27899083, 2016). "Similar results have been reported in human breast cancer for both ESR1 and PGR expression." (PMID 27649560, 2016). "Triple-negative breast tumors represent a breast cancer subtype that is characterized by the lack of estrogen receptor (ER) and progesterone receptor (PR) expression and does not overexpress the HER2 receptor." (PMID 27418135, 2016). "Based on the immunohistochemical analysis, triple-negative breast cancers (TNBCs) have been identified as breast cancers that do not express oestrogen receptorα (ERα), progesterone receptor (PR) and Her-2 (triple-negative immunophenotype)." (PMID 27884978, 2016). "According to the receptor status classification based on estrogen receptor (ER), progesterone receptor (PR) and human epidermal growth factor receptor 2 (HER-2) positivity, breast cancer can be divided into luminal A, luminal B, HER2 type and triple negative/basal - like subtype." (PMID 27460922, 2016). "Of several subtypes of breast cancer, the most aggressive form is characterised by absence of estrogen receptor (ER), progesterone receptor (PR) and human epidermal growth receptor 2 (HER2) and designated as triple negative breast cancer (TNBC)." (PMID 27404381, 2016). "Thus, the aim of this study was to investigate the value of established prognostic markers (such as ER, PGR, HER-2) and WNT components in liver metastases of breast cancer and matched primaries." (PMID 26862065, 2016). "We hypothesized that a combination of estradiol (E2) with selective progesterone receptor modulator (SPRM) to exert a safer profile on endometrium will also reduce mammary gland proliferation and could be used to prevent breast cancer when used in MHT." (PMID 27011208, 2016). "AA breast cancer patients are more likely to have disadvantageous tumor subtypes, such as estrogen receptor (ER) negative, progesterone receptor (PR) negative, and triple negative breast cancer." (PMID 27314854, 2016). "Triple-negative breast cancer (TNBC), which accounts for 20 % of all breast cancers, is characterized by the absence of estrogen receptor (ER), progesterone receptor (PR), and human epidermal growth factor receptor 2 (HER2) expression." (PMID 26757880, 2016). "Histological and molecular analysis of the breast cancer revealed it to be an invasive ductal carcinoma with a predominant ductal component, estrogen receptor–negative, progesterone receptor–negative, and HeR2-positive." (PMID 27900359, 2016). "Claudin-low mammary tumors are a subset of basal-like breast cancers that are typically estrogen receptor, progesterone receptor and HER2 negative, express low levels of claudins 2, 4 and 7 and have characteristics of progenitor cells." (PMID 27282619, 2016). "TNBC is a distinct pathological subgroup of breast cancer without estrogen receptor (ER), progesterone receptor (PR) and human epidermal growth factor receptor 2 (HER-2)." (PMID 27879682, 2016). "ER's target genes, PGR and CCND1 were also overexpressed in MALAT1 altered group, indicating MALAT1 might play a role the regulation of ER expression in breast cancer." (PMID 27191888, 2016). "Ly6H mRNA expression was significantly higher in progesterone receptor (PgR) positive breast cancer (n=215) than PgR negative breast cancer (n=149) in Stickeler and TCGA (Unpublished, NCI) and Chang studies." (PMID 26862846, 2016).
breast cancer (continued). "Triple-negative breast cancer (TNBC) comprises 15% of all breast cancers and is characterized by the absence of expression of estrogen receptor (ER), progesterone receptor (PR), and the human epidermal growth factor receptor 2 (HER2)." (PMID 28721372, 2016). "According to correlation analyses between gene expression and phosphorylated protein expression in both cell lines and tumors, significant results are found that important drug targets in breast cancer, such as ESR1, PGR, HER2, EGFR and AR show high correlated mRNA and protein levels." (PMID 27556158, 2016). "Triple negative breast cancer (TNBC) is a subgroup of breast cancer lacking estrogen receptor (ER) and progesterone receptor (PR) expression as well as human epithelial growth factor receptor 2 (HER2) amplification." (PMID 27145269, 2016). "Triple-negative breast cancer (TNBC) is characterized by estrogen receptor (ER) and progesterone receptor (PR) negative, and lack of human epidermal growth factor receptor type 2 overexpression, accounting for 10%–20% of breast cancer cases." (PMID 28036090, 2016). "For therapeutic purposes, breast cancer has been historically classified based on the expression or lack of expression of estrogen receptor (ER), progesterone receptor (PR), and human epidermal growth factor receptor (HER2)." (PMID 27918430, 2016). "Triple-negative breast cancer (TNBC) is a heterogeneous collection of breast cancers lacking expression of estrogen receptor (ER), progesterone receptor (PR), and human epidermal growth factor receptor 2 (HER2) amplification." (PMID 27310713, 2016). "Frequent diagnosis of aggressive triple negative (TN) (ER-, progesterone receptor negative (PR-) and Her2 Neu-) form of breast cancer in young African American (AA) women suggest disparity in development of this deadly disease." (PMID 27473585, 2016). "It has been shown that MDA-MB-231 is an invasive breast cancer cell line which does not express ER and progesterone receptor (PR), and does not have HER-2/Neu amplification." (PMID 27540529, 2016). "To better study the influence of degree and pattern of HRs expression on clinical behavior and trastuzumab efficacy, we recruited 872 patients with TP breast cancer selected on the basis of a HER2-positive status and simultaneous expression of both ER and PgR in at least 1% of the tumor cells." (PMID 26910921, 2016). "Triple-negative breast cancer (TNBC) accounts for 15–20 % of all breast cancer cases and is characterized by lack of estrogen- and progesterone receptor (ER, PR)-expression as well as lack of human epidermal growth factor receptor-2 (HER2) amplification." (PMID 27756336, 2016). "Triple negative breast cancers are an aggressive subtype of breast cancer, characterized by the lack of estrogen receptor, progesterone receptor and Her2 expression." (PMID 27283985, 2016). "Triple negative breast cancer (TNBC) accounts for 10–20 % of all breast carcinomas and is characterized by the absence of estrogen receptor (ER), progesterone receptor (PR) and human epidermal growth factor receptor 2 (HER-2)." (PMID 27282478, 2016). "Triple-negative breast cancers (TNBCs) have been classified as a breast carcinoma subgroup which is negative for estrogen receptor (ER), progesterone receptor (PgR) and HER2 expression." (PMID 27323808, 2016). "Triple-negative breast cancer (TNBC) is a form of breast cancer that does not express oestrogen receptor, progesterone receptor, and HER2." (PMID 25426559, 2015). "Basal-like breast carcinomas belong to the triple-negative (TN) breast cancers family, with no expression of estrogen receptor (ER), progesterone receptor (PR) and no HER2 overexpression (amplification)." (PMID 26426992, 2015). "The clinical significance of progesterone receptor (PgR) expression in estrogen receptor-negative (ER–) breast cancer is controversial." (PMID 26437901, 2015).
breast cancer (continued). "The estrogen receptor (ER), the progesterone receptor (PR) and human epidermal growth factor receptor 2 (HER2) are the molecular biomarkers currently used in routine clinical practice to help make treatment decisions for breast cancer." (PMID 26036638, 2015). "Triple-negative breast cancer (TNBC) refers to breast cancers that do not express the genes for estrogen receptor (ER), progesterone receptor (PR) and the Her2/neu receptor and accounts for about 20% of breast cancers." (PMID 25927362, 2015). "Although collected data about the number of years from recent childbirth from 207 cases was limited in this study, the breast cancer patients who had given birth more recently showed an increased rate of PgR-negative tumors in another report." (PMID 26207196, 2015). "Triple-negative breast cancer (TNBC) comprises 10 % to 20 % of breast cancers and is characterized by a lack of estrogen receptor (ER), progesterone receptor (PgR), and human epidermal growth factor receptor-2 (HER2) expression." (PMID 26341640, 2015). "Of these, 56 patients (6.9%) had ER-/PgR+ breast cancers, while 624 (76.6%) had ER+ tumors irrespective of PgR expression (ER+/PgR-any) and 136 (16.7%) had ER-/PgR- tumors." (PMID 26161666, 2015). "CD44 expression is selectively over-expressed in estrogen receptor (ER)- and progesterone receptor (PR)-negative breast tumors, with enrichment detected in basal-like breast cancer (BLBC)." (PMID 26447611, 2015). "Gallen consensus on early-stage breast cancer recommends making clinical treatment decisions based on the surrogates of molecular subtypes (luminal-A, luminal-B, HER2-positive, and basal-like) defined by ER, PgR, HER2, and Ki67." (PMID 26437901, 2015). "It remains the primary therapeutic agent for the management of ER and/or progesterone receptor (PR)-expressing breast cancers, particularly in premenopausal women without or with conventional chemotherapeutics." (PMID 26206152, 2015). "Triple negative breast cancer (TNBC) is an aggressive breast cancer subtype lacking estrogen receptor (ER) and progesterone receptor (PR) expression and human epidermal growth factor receptor 2 (HER2) gene amplification." (PMID 25583261, 2015). "TNBC is an aggressive breast cancer characterized by the absence of estrogen receptor (ER) and progesterone receptor (PR) as well as a lack of over-expression of the HER2/Neu receptor." (PMID 25779666, 2015). "Although the BRCA1 mutation is related to triple negative breast cancer, a family history of breast cancer did not influence hormonal sensitivity in this study, as three of five cases in the Younger than 30 group were PgR-positive." (PMID 26207196, 2015). "The purpose of this study was to assess whether breast cancer subtype (BCS) as determined by estrogen receptor, progesterone receptor, and human epidermal growth factor receptor 2 can predict the axillary lymph node metastasis in breast cancer." (PMID 26632910, 2015). "In breast cancer, exosomal miR-373 expression was elevated in triple negative disease compared with luminal tumors and in oestrogen and progesterone receptor negative breast cancers compared with hormone receptor positive control subjects." (PMID 29861415, 2015). "TMEM47 displayed prognostic value in estrogen receptor and progesterone negative but not in estrogen receptor and progesterone receptor positive breast cancer (data not shown)." (PMID 25926557, 2015). "The BT20 breast cancer cells used in these experiments were isolated from a breast tumor that was triple negative for the expression of Her2, estrogen receptor and progesterone receptor." (PMID 26053043, 2015). "Although EGFR is rarely mutated in breast cancers, the wild type protein is frequently overexpressed in breast tumors, and EGFR has been suggested to be a therapeutic target in triple-negative (Estrogen Receptor-, Progesterone Receptor-, and HER2-negative) breast cancers." (PMID 25865227, 2015).